SIRT1 (sirtuin 1)
Diseases named in the same sentence as SIRT1 in open-access papers (continued):
Sharing a sentence is not in itself a finding about the gene and the disease.
Hepatic steatosis (continued). "Therefore, the SIRT1-AMPK phosphorylation signaling pathway functions in the regulation of lipid metabolic homeostasis and may be a new therapeutic target for hepatic steatosis." (PMID 41223206, 2025). "Interestingly, even the induction of a mild liver steatosis with a low percentage of fructose for a relatively short period of time resulted in an increase in the protein levels of VLDLR, while the protein levels of SIRT1 were reduced." (PMID 38807218, 2024). "SIRT1 overexpression using adenovirus can reduce PGC-1α acetylation level and induced PPARα transcriptional signalling, as well as the expression of PPARα/PGC-1α targeting genes, thereby increasing FAO, and alleviating MASLD in mice with HFD-induced hepatic steatosis." (PMID 39264516, 2024). "Moreover, other studies administrating chemical activators of SIRT1, resveratrol and SRT1720, or the NAD+ precursor nicotinamide riboside, reduced SREBP1c, FAS, SCD1 gene and protein expression in the liver of mice/rats with HFD-induced hepatic steatosis." (PMID 39264516, 2024). "Concerning SIRT1, a trial conducted in obese patients with MASLD showed a lower plasma SIRT1 levels in patients with either moderate or severe liver steatosis compared to the mild steatosis group, and that plasma SIRT1 negatively correlated with liver steatosis." (PMID 39264516, 2024). "A study on the therapeutic effects of Naringenin on NASH showed that Naringenin improves hepatic steatosis, hepatic fibrosis, hepatic inflammation, and hepatic oxidative stress in NASH mice, and it suggests that Naringenin exerts its therapeutic effects through SIRT1." (PMID 38115075, 2023). "Therefore, decreased sirtuin-1 expression and activity in IUGR male livers might have modulated the expression of these lipogenic genes and induced the liver steatosis we observed." (PMID 36139771, 2022). "On the other hand, SIRT1 could be interacted with and subsequently degraded through ubiquitination by the gene related to energy in lymphocytes (GRAIL), which was upregulated in the livers of humans and mice with hepatic steatosis." (PMID 35945571, 2022). "The effect of Sirt1 on HPCs in fatty liver injury is not reported, thus, we hypothesize presently that Sirt1 plays a key role in liver repair and regeneration mediated by HPCs in the NAFLD model with liver fatty injury." (PMID 34977130, 2021). "For example, mammalian sirtuins (SIRTs), NAD-dependent histone deacetylase such as SIRT1 and SIRT3, were involved in oxidative stress and lipid metabolism regulation, and had been proposed as a reliable biomarker and/or therapeutic target for fatty liver disease." (PMID 34481473, 2021). "COX-2 overexpression did not change the SIRT1 protein level under either diet, indicating that SIRT1 participates in the HF+Eth diet-induced liver steatosis, but did not contribute significantly to the protective function of COX-2 TG in HF+Eth-induced metabolic dysfunction." (PMID 33662521, 2021). "Interestingly however, exercise-trained GCN2KO mice were better protected against hepatic steatosis with downregulated expressions of p-eIF2α and ATF4, upregulated expressions of p-AMPK and SIRT1, and the presence of PPARα in the liver, compared to the exercised WT mice." (PMID 33299856, 2020). "Mammalian sirtuins (SIRTs) is an important type of NAD-dependent histone deacetylase, such as SIRT1 and SIRT3, were involved in oxidative stress and lipid metabolism regulation, and had been proposed as a reliable biomarker and/or therapeutic target for fatty liver disease." (PMID 32586350, 2020). "HepG2 cells were pretreated with CT and/or compound C (AMPK Inhibitor) and Ex52735 (SIRT1 inhibitor) before treatment with ethanol and TG accumulation was evaluated to further examine the role of AMPK/SIRT1 in CT-mediated protection against ethanol-induced hepatic steatosis." (PMID 31906014, 2019).
Hepatic steatosis (continued). "Importantly, compound C (AMPK inhibitor) significantly blocked the CT-mediated reduction in TG accumulation, but not Ex52735 (SIRT1 inhibitor), which suggested that CT countering ethanol-promoted hepatic steatosis is mediated by AMPK activation." (PMID 31906014, 2019). "Moreover, in fatty liver disease, ROS-induced oxidative stress can inhibit the expression of energy metabolism signaling pathway-related proteins such as AMPK, Sirtuin 1 (SIRT1), and the transcription factor signal transducer and activator of transcription 3 (STAT3)." (PMID 31159489, 2019). "There was no paper mentioned about whether SIRT1 was involved in the prenatal dexamethasone liver steatosis model, and this needs further study to prove." (PMID 30424542, 2018). "We conclude that the SIRT1-autophagy pathway and decreased ER stress are universally required for the protective effects of moderate caloric restriction (30%) and resveratrol (a pharmacological SIRT1 activator) supplementation against HFD-induced hepatic steatosis." (PMID 28817690, 2017). "In our present study, the decreased protein level of SIRT1 and its activity, as evidenced by increased acylated-FOXO1, resulted in the increased proteins level of ACC and SCD1, which supported the role of SIRT1 in mediating hepatic steatosis induced by HCLD feeding." (PMID 26608583, 2015). "Mechanistically, RSV could ameliorate NAFLD and hepatic steatosis in obese mice by promoting the SIRT1/AMPK pathway, possibly mediated by activating SIRT11 as a Sirt1 enhancer, and ameliorating the accumulation of LDs by mediating a SIRT1/ATF6-dependent mechanism." (PMID 35431994, 2022). "Irrespective of the group of patients, SIRT1, adiponectin and leptin showed a substantially overlapping strength of prediction for EFT and liver steatosis." (PMID 33202604, 2020). "Our results suggest that the reduction of ROS production secondary to the absence of neutrophilic NCF1 leads to hepatic activation of SIRT1 and AMPK, shifts the intracellular lipid metabolism toward fatty acid oxidation, and ameliorates alcohol-induced hepatic steatosis." (PMID 35838051, 2022). "In addition, when Sirt1 was downregulated by AAV9-shRNAs, Gly-tRF inhibitor did not further ameliorate liver steatosis in mice." (PMID 31076642, 2019). "However, co-treatment with compound C significantly blocked the CT-mediated reduction in TG accumulation, but not Ex52735 (SIRT1 inhibitor), which suggested that AMPK, as an upstream of SIRT1, mediates CT-induced protection against ethanol-promoted hepatic steatosis." (PMID 31906014, 2019).
breast cancer (329 papers, 2006 to 2026). A primary or metastatic malignant neoplasm involving the breast. "Elevated expression of SIRT1 has also been associated with higher rates of metastasis in TNBC but lower rates in all other types of breast cancer." (PMID 40165290, 2025). "SIRT1 has been implicated in modulating the sensitivity of HER2+ breast cancer cells to targeted therapies." (PMID 41300302, 2025). "As in breast cancer, in the context of gynecologic malignancies (such as ovarian cancer, endometrial cancer and cervical cancer), SIRT1 has been implicated in both tumor suppression and tumor progression, depending on the cellular context." (PMID 41300302, 2025). "Overall, SIRT1 overexpression in breast cancer is associated with increased malignancy, resistance to oxidative stress, and poor clinical outcomes, positioning SIRT1 as a key modulator of redox signaling and therapeutic escape." (PMID 41008982, 2025). "As documented in recent studies, SIRT1 has also been identified as being overexpressed in breast cancer tissues, where it is associated with worse overall survival and a higher possibility for metastasis." (PMID 39456765, 2024). "Sirt1 and FoxO have also been associated with breast cancer progression and metastasis, although the signaling mechanisms underlying their involvement still need to be investigated." (PMID 39202438, 2024). "SIRT1 expression is upregulated by estradiol at the mRNA and protein levels in SkBr3 (breast cancer cells) and CAFs (cancer-associated fibroblasts)." (PMID 37762053, 2023). "Another SIRT1 genetic variant, rs3758391, is a polymorphism that has been associated with various diseases such as type 2 diabetes, breast cancer, autoimmune thyroid disease, lupus erythematosus, and others." (PMID 37892107, 2023). "Greater expression of SIRT1 is positively associated with greater expression of ERα in breast cancer cells." (PMID 37762053, 2023). "SIRT4, able to inhibit cancer stem cells proliferation and survival, is found downregulated in breast cancer, and its levels are inversely correlated to SIRT1 expression and linked to acquisition of breast cancer aggressive phenotype." (PMID 35328633, 2022). "High expression levels of SIRT1 cause increased invasion in breast cancer cells, whereas SIRT1 inhibition by shRNA decreases the invasion of breast cancer cells." (PMID 36142156, 2022). "For the first time in the literature, our results show that SIRT1 and FoxO proteins are associated with metastasis of breast cancer." (PMID 36142156, 2022). "As an elementary investigation of the molecular mechanisms related to SIRT1/FoxO underlying breast cancer, microarray data were submitted to IPA (ingenuity pathway analysis)." (PMID 36142156, 2022). "Breast cancer has been investigated with SIRT-1 inhibitors: two studies with EX-527 showed that it causes cell cycle arrest and suppresses the resistance to Hsp90 inhibitors in cancer cells." (PMID 36080416, 2022). "They further demonstrated that miR-200a expression or SIRT1 knockdown prevents the transformation of normal mammary epithelial cells and that overexpression of SIRT1 is associated with decreased miR-200a in breast cancer patients." (PMID 36291902, 2022). "Through targeting Bcl-2, CD44, and SIRT1 (silent information regulator 1), Rac1, Fra-1, Notch-1, and different cyclins, exogenous expression of miR-34a in breast cancer cells caused cell death and decreased cell proliferation and migration." (PMID 36325275, 2022). "Collectively, these data suggest that dunnione alleviates breast cancer-associated lung thrombosis by inhibiting the expression of tissue factor through the NAD+/SIRT1/acetyl-NF-κB/tissue factor axis in vivo." (PMID 34769515, 2021). "On the other hand, Sirt1/2/3 and 7 are implicated in breast cancer initiation, progression, metastasis, and multidrug resistance." (PMID 33430318, 2021). "As reported, decreased sirtuin 1 (SIRT1) expression is associated with the metastatic spread of breast cancer cells." (PMID 34485600, 2021).
breast cancer (continued). "For example, in HMLER breast cancer cells, reduced SIRT1 levels are associated with increased metastases 10, whilst high SIRT1 expression promoted tumorigenesis and is associated with poor prognosis in colorectal carcinoma patients." (PMID 32489467, 2020). "Experiments on nude mice have shown that SIRT1 promotes invasion and metastasis in breast cancer when it is weakly expressed, and the loss of SIRT1 in renal tubular epithelial cells exacerbates injury-induced kidney fibrosis." (PMID 31817470, 2019). "This inverse correlation provides a causal link between the expression patterns of SIRT1 and the 3 epi-marks in human breast cancer." (PMID 30093977, 2018). "In breast cancer patients, decrease of SIRT1 was associated with reduced PRRX1 but increased KLF4, and the latter was positively correlated with distal metastases (P<0.001, χ2 test)." (PMID 30038266, 2018). "Having uncovered the role of SIRT1 deficiency in promoting breast cancer stemness, we then sought to identify its downstream effectors." (PMID 30038266, 2018). "All the meta-analyses studies revealed a significant association between high SIRT1 with poor OS in these solid carcinomas including breast cancer, hepatocellular carcinoma, colorectal cancer, lung cancer, liver cancer." (PMID 29088792, 2017). "A recent study found mutations in the SIRT1 gene in several breast cancer cell lines that were related to breast cancer progression." (PMID 28197299, 2017). "The present study aimed to assess the association between SIRT1 gene polymorphisms and breast cancer in Egyptians." (PMID 26999517, 2016). "Our observations regarding serum SIRT1 levels provide a potential mechanism for the association of the studied SNPs with genetic susceptibility to breast cancer." (PMID 26999517, 2016). "The genotype distribution and allele frequency of SIRT1 promoter region polymorphisms rs3758391, rs3740051 and rs12778366 were compared between breast cancer patients and normal subjects." (PMID 26999517, 2016). "This is the first study to assess the association between genetic variation in SIRT1 and susceptibility and prognosis of breast cancer." (PMID 26999517, 2016). "Our findings reveal that rs3758391 and rs12778366 polymorphisms of SIRT1 gene are associated with breast cancer risk and prognosis in the Egyptian population." (PMID 26999517, 2016). "In this study, we demonstrated the effect of MSCs with Sirt1 overexpression (MSCs-Sirt1) in mice bearing 4T1 breast cancer and investigated the underlying mechanism." (PMID 27782173, 2016). "Accordingly, the current findings would highly recommend that women, particularly Egyptians, with a strong family history of breast cancer should be genetically tested for SIRT1 rs3758391 and rs12778366 genetic variants to predict risk of breast cancer." (PMID 26999517, 2016). "Comparing SIRT1 rs3758391 genotype and allele distributions between breast cancer patients and normal subjects revealed significantly higher frequencies of the TT genotype and the T allele in breast cancer patients than in normal controls." (PMID 26999517, 2016). "The pathogenesis of breast cancer is multifactorial; however, the association of SIRT1 expression with the clinical characteristics and prognosis in breast cancer has not been fully identified." (PMID 26999517, 2016). "Our findings suggest a role of genetic variation in SIRT1 at the studied loci as a risk factor and as a prognostic factor for breast cancer in the Egyptian population." (PMID 26999517, 2016). "The oncogenic role of SIRT1 is further supported by our observation of significant association of breast cancer with the genotypes having higher SIRT1 levels in each of the studied SNPs." (PMID 26999517, 2016).
breast cancer (continued). "Statistical analysis of the correlation between SIRT1 rs3758391 and clinicopathological parameters in breast cancer patients revealed highly significant associations with histologic grade and lymph node status." (PMID 26999517, 2016). "Another important role for SIRT1 in cancer is its suppression of the apoptosis inhibitor survivin in breast cancer susceptibility gene 1 (BRCA1)-associated breast cancers." (PMID 25486244, 2014). "Our results suggest that, of these proteins, only the low expression of SIRT1 alone, and the combined expression of SIRT1-low/N1IC-high are significantly associated with worse survival in breast cancer patients." (PMID 25420528, 2014). "In our study, SIRT1 was highly expressed in 77.3% (116/150) breast cancer patients, and SIRT1 over-expression was associated with prolonged survival." (PMID 25420528, 2014). "A relatively scant amount of clinical data has suggested an oncogenic role for SIRT1 in breast cancer, however many breast cancer cell lines have lost Sirt1 alleles or contain mutations in the Sirt1 gene, suggesting a role as a non-classical tumor suppressor." (PMID 25380034, 2014). "Some studies have found that SIRT1 expression is significantly associated with poor survival, while, in contrast, others reported an association with good prognosis in breast carcinoma." (PMID 25420528, 2014). "The role of SIRT1 in breast carcinoma, and especially its association with outcome, is a cause for much debate due to conflicting reports of its dual role as an oncogene and a tumor suppressor gene." (PMID 25420528, 2014). "In breast cancer, extremely limited clinical evidence suggests that SIRT1 expression is associated with poorer prognosis, implying that SIRT1 has a pro-oncogenic effect." (PMID 24278473, 2013). "We introduced the MMTV-PyMT transgene into stocks of mice carrying the H355Y point mutation in the Sirt1 gene (an allele referred to as Sirt1Y) and studied the emergence of mammary tumors in Sirt1+/+, Sirt1+/Y, and Sirt1Y/Y females." (PMID 24278473, 2013). "In contrast, both nuclear and cytoplasmic expression of SIRT1 associated with poor prognosis of breast carcinoma patients." (PMID 24019980, 2013). "Included among these are Sirt1, Hey2, Ncoa4, and Foxa1, all of which have been implicated in the progression of luminal breast cancer and ER-α-dependent signaling, as well as ER-α (that is, Esr 1)." (PMID 20565980, 2010). "Assessing the potential correlation between the enzymatic activity of SirT1 and the risk of breast cancer is therefore of great interest in order to identify feasible targets for chemoprevention against breast cancer." (PMID 17201918, 2007). "Also, the extensively high SIRT1 protein levels in breast carcinoma have been found to be associated with tumor promotion and a worse prognosis." (PMID 39858444, 2025). "The findings of the study on breast cancer indicated higher serum SIRT1 expression levels to be associated with the rs12778366 TT genotype in breast cancer cases, which was also associated with an increased risk of breast cancer, suggesting a tumour promoting role of SIRT142." (PMID 32098999, 2020). "Besides, the Akt pathway is also associated with the activity of SIRT1 in promoting breast cancer progression." (PMID 33193750, 2020). "The SIRT1 rs12778366 polymorphism was found to have a relation with breast cancer." (PMID 31747893, 2019). "It was found that Rs12778366 polymorphism of SIRT1 gene is associated with breast cancer." (PMID 31781300, 2019). "In breast cancer and fatty liver-associated liver cancer, O-GlcNAcylation was previously thought to be a central component linking metabolism to invasion and metastasis via the SIRT1/FOXM1 axis." (PMID 30093632, 2019). "Previous study also showed that SIRT1 activity is required for suppressing survivin transcription, and reduction of survivin via SIRT1 activity may play an important role in breast cancer susceptibility gene 1 (BRCA1)-associated mammary tumor formation." (PMID 29636061, 2018).